GPR68 (G protein-coupled receptor 68)
Description:
Proton-sensing G protein-coupled receptor activated by extracellular pH, which is required to monitor pH changes and generate adaptive reactions. The receptor is almost silent at pH 7.8 but fully activated at pH 6.8. Ligand binding causes a conformation change that triggers signaling via guanine nucleotide-binding proteins (G proteins) and modulates the activity of downstream effectors, such as phospholipase C. GPR68 is mainly coupled to G(q) G proteins and mediates production of diacylglycerol (DAG) and inositol 1,4,5-trisphosphate (IP3). Acts as a key mechanosensor of fluid shear stress and membrane stretch. Expressed in endothelial cells of small-diameter resistance arteries, where it mediates flow-induced dilation in response to shear stress. May represents an osteoblastic pH sensor regulating cell-mediated responses to acidosis in bone (By similarity). Acts as a regulator of calcium-sensing receptor CASR in a seesaw manner: GPR68-mediated signaling inhibits CASR signaling in response to protons, while CASR inhibits GPR68 in presence of extracellular calcium (By similarity).
Synonyms: GPR12A; OGR1; AI2A6
Tractability: Small molecule: a structure with a bound ligand is known; it belongs to a druggable protein family. Antibody: UniProt places it where antibodies can reach, with high confidence; its Gene Ontology location is reachable by antibodies, with high confidence; UniProt predicts a signal peptide or a membrane-spanning region. PROTAC: a small molecule that binds it is known.
Target class: Family A G protein-coupled receptor; Membrane receptor
Chemical probes: ZINC67740571 (high quality)
Gene: Protein-coding gene on chromosome 14 (91,232,532 to 91,254,026, reverse strand). Ensembl gene ENSG00000119714.
Subcellular location: Cell membrane
Pathways (Reactome):
Signal Transduction: Class A/1 (Rhodopsin-like receptors); G alpha (q) signalling events
Gene Ontology:
Molecular function: G protein-coupled receptor activity; protein binding
Biological process: adenylate cyclase-activating G protein-coupled receptor signaling pathway; cellular response to acidic pH; phospholipase C-activating G protein-coupled receptor signaling pathway; response to fluid shear stress; cellular response to pH; G protein-coupled receptor signaling pathway; inflammatory response
Cellular component: plasma membrane; membrane
Genetic constraint (gnomAD): Loss-of-function variants: 11 observed, 15.78 expected, observed/expected ratio (o/e) 0.7, 90% interval 0.44 to 1.15. The synonymous counts are far from expectation, so gnomAD's model fits this gene poorly and the ratio says little. Missense variants: 498 observed, 458.82 expected, observed/expected ratio (o/e) 1.09, 90% interval 1.01 to 1.17. Synonymous variants: 262 observed, 208.97 expected, observed/expected ratio (o/e) 1.25, 90% interval 1.13 to 1.39.
Homologues: Orthologues: chimpanzee GPR68 (99% identical), macaque GPR68 (98% identical), rat Gpr68 (93% identical), rabbit GPR68 (93% identical), mouse Gpr68 (92% identical), guinea pig GPR68 (90% identical), pig GPR68 (88% identical), dog GPR68 (86% identical), tropical clawed frog gpr68 (57% identical), zebrafish GPR68 (49% identical). Paralogues in human: LPAR5 (25% identical).
Diseases named in the same sentence as GPR68 in open-access papers:
GPR68 is named in the same sentence as 133 diseases in open-access papers, as found by Europe PMC text mining. Sharing a sentence is not in itself a finding about the gene and the disease. The quoted sentences say what the papers report.
ovarian carcinoma (67 papers, 2009 to 2025). A malignant neoplasm originating from the surface ovarian epithelium. "Proton-sensing GPCRs—notably GPR4, GPR65 (also known as T-cell death-associated gene 8, TDAG8), and GPR68 (also known as ovarian cancer G-protein-coupled receptor 1, OGR1)—are transmembrane receptors that detect extracellular acidification." (PMID 41375084, 2025). "pHRs are class A GPCRs that consist of three members, G protein coupled receptor 4 (GPR4), T cell death-associated gene 8 (TDAG8, aka GPR65) and ovarian cancer G-protein coupled receptor 1 (OGR1, aka GPR68)." (PMID 38340167, 2024). "G-protein-coupled receptors (GPRs), including pro-inflammatory ovarian cancer GPR1 (OGR1/GPR68) and anti-inflammatory T cell death-associated gene 8 (TDAG8/GPR65), are involved in pH sensing and linked to inflammatory bowel disease (IBD)." (PMID 37834303, 2023). "The family includes T-cell death-associated gene 8 (TDAG8 or GPR65), ovarian cancer G-protein coupled receptor 1 (OGR1 or GPR68), G2 accumulating protein (G2A or GPR132), and GPR4." (PMID 36233248, 2022). "A family of G protein-coupled receptors (GPCRs): including ovarian cancer G-protein coupled receptor 1 (OGR1, also known as GPR68), GPR4 and T-cell death associated gene 8 (TDAG8, also known as GPR65), are activated by acidic extracellular pH." (PMID 31996710, 2020). "The family of proton-sensing GPCRs include four members: GPR4, GPR65, or T-cell death-associated gene 8 (TDAG8), GPR68, or Ovarian cancer G protein-coupled receptor 1 (OGR1) and GPR132 or G2A." (PMID 33113952, 2020). "This subfamily of proteins is composed of four members: G protein-coupled receptor 4 (GPR4 or Gpr4), T-cell death–associated gene 8 (TDAG8 or Gpr65), ovarian cancer G protein–coupled receptor 1 (OGR1 or Gpr68), and G protein–coupled receptor 132 (G2A or Gpr132)." (PMID 35247105, 2022). "Accordingly, the harmful impact of lorazepam relied on positive allosteric modulation of ovarian cancer G-protein-coupled receptor 1 (OGR1 or GPR68)." (PMID 40061137, 2025). "This includes G-protein receptor 4 (GPR4), T cell death-associated gene 8 (TDAC8, or GPR65), and ovarian cancer G-protein coupled receptor 1 (OGR1, or GPR68)." (PMID 41091845, 2025). "GPR68, alternatively referred to as ovarian cancer G protein-coupled receptor 1, was initially identified in a human ovarian cancer cell line HEY." (PMID 41190345, 2025). "G protein-coupled receptors (GPRs), including pro-inflammatory GPR4 and ovarian cancer GPR1 (OGR1/GPR68), are involved in the pH sensing of the extracellular space and have been implicated in inflammatory bowel disease (IBD)." (PMID 40004018, 2025). "Examples include the endothelial cell GPCR GPR68 or OGR1 (ovarian cancer G protein-coupled receptor 1)." (PMID 39334952, 2024). "The expression of pH-sensing ovarian cancer G-protein coupled receptor-1 [OGR1/GPR68] was found to be elevated in the ileal samples of fibrostenotic patients and positively correlated with the expression of pro-fibrotic cytokines and pro-collagens (p = 0.016)." (PMID 38399592, 2024). "GPR68, also known as ovarian cancer G-coupled protein receptor 1 (OGR-1), is a member of the proton sensing GPCR family which is activated in response to subtle extracellular acidification (inactive at pH 7.4 and fully active at pH 6.4)." (PMID 38291540, 2024). "In response to acidic extracellular pH, GPR65 induces an anti-inflammatory response, whereas the two other proton-sensing receptors, GPR4 and GPR68 (ovarian cancer G protein-coupled receptor 1, OGR1), mediate pro-inflammatory responses." (PMID 38514581, 2024). "Originally identified from HEY cells, an ovarian cancer cell line, GPR68 expression is upregulated in multiple types of cancers, such as colon cancer, pancreatic cancer, and breast cancer." (PMID 39336742, 2024). "GPR68, also known as ovarian cancer G protein-coupled receptor 1 (OGR1), is a proton-sensing G-protein-coupled receptor that responds to extracellular acidity." (PMID 36611126, 2023).
ovarian carcinoma (continued). "In human ovarian cancer cells, GPR68 improves tumor cell adhesion to extracellular matrix, but surprisingly inhibits cell proliferation and migration." (PMID 36902589, 2023). "GPR68, or ovarian cancer G protein-coupled receptor 1, responds to extracellular acidity and is highly expressed in head and neck squamous cell carcinoma (HNSCC) as well as normal esophageal tissue." (PMID 36611126, 2023). "Here, we report that the Ovarian Cancer G-Protein Coupled Receptor1 (OGR1 or GPR68) has dual roles in both promoting and mitigating pulmonary fibrosis." (PMID 36010617, 2022). "Proton-sensing ovarian cancer G-protein-coupled receptor 1 (OGR1, also known as GPR68) responds to decreases in extracellular pH." (PMID 35163345, 2022). "GPR68, a family of the G protein-coupled receptors, is also known as ovarian cancer G protein-coupled receptor 1 (OGR1)." (PMID 35123428, 2022). "Among the members of the proton sensing GPCRs is GPR68, also known as ovarian cancer G protein-coupled receptor 1 (OGR1)." (PMID 35311103, 2022). "The tumor suppressor gene GPR68, known as ovarian cancer G protein-coupled receptor 1 (OGR1), is a transmembrane receptor of the proton-sensing G protein-coupled receptors that is activated when extracellular levels of PH are altered." (PMID 34715892, 2021). "It belongs to a small G protein-coupled proton-sensing receptor family that includes ovarian cancer G protein-coupled receptor 1 (OGR1), also referred to as GPR68, G2A, also termed GPR132, and T-cell death-associated gene 8 (TDAG8), also known as GPR65." (PMID 33053856, 2020). "In human ovarian cancer cells, GPR68 has been shown to promote adhesion of cells to the extracellular matrix." (PMID 31236404, 2019). "GPR68 (or ovarian cancer G protein-coupled receptor 1, OGR1) is a proton-sensing G-protein-coupled receptor (GPCR) that responds to extracellular acidity and regulates a variety of cellular functions." (PMID 30696114, 2019). "The G protein-coupled receptor 68 (GPR68, also known as ovarian cancer G-protein coupled receptor; OGR1) was similarly overexpressed in transitional carriers." (PMID 29259271, 2017). "Recent evidence suggests that ovarian cancer G protein-coupled receptor 1 (OGR1/GPR68) and other members of the OGR1-family of G protein-coupled receptors (GPCRs) are sensors of the mild decreases in extracellular pH that occur under inflammatory conditions." (PMID 26828924, 2016). "Conversely, ovarian cancer G protein-coupled receptor 1 (OGR1, GPR68) is expressed in various cell types, including highly mobile leukocytes such as monocytes/macrophages, T cells, granulocytes, and various mesenchymal cell lineages that still retain some degree of mobility." (PMID 40004018, 2025). "Similarly, GPR68 also known as ovarian cancer G protein-coupled receptor 1 (OGR1) has also been identified as a proton sensing receptor." (PMID 35625966, 2022). "In ovarian cancer, GPR68 is coupled to the PLC/Ca2+ pathway via the Gq/11 protein." (PMID 31236404, 2019). "Similar effects have been observed in GPR68-overexpressing human ovarian cancer HEY cells." (PMID 30696114, 2019). "In HEY human ovarian cancer cells, MCF-7 breast cancer cells, and Caco-2 colorectal adenocarcinoma cells, increased GPR68 expression is associated with reduced cell proliferation and migration, suggesting GPR68 may act as a tumour suppressor." (PMID 31652823, 2019). "GPR68, or the ovarian cancer G protein-coupled receptor 1 (OGR1), so called as it was first cloned from an ovarian cancer cell line, stimulates the accumulation of inositol phosphates and mobilization of intracellular Ca2+ in response to extracellular acidosis within the range of pH 7.6–6.8." (PMID 31544616, 2019). "Recent studies have identified lactate as a ligand for GPR68, GPR81, and GPR132, also known as ovarian cancer G protein-coupled receptor 1 (OGR1), hydroxy-carboxylic acid receptor 1 (HCAR1) and G2 accumulation protein (G2A), respectively." (PMID 40046050, 2025).
ovarian carcinoma (continued). "When overexpressed, GPR68 has been shown to inhibit the migration of PC3 prostate cancer cells, HEY ovarian cancer cells, MCF7 breast cancer cells, Caco-2 colon cancer cells, and A549 lung cancer cells." (PMID 39336742, 2024). "There are four members within this family of receptors, the Ovarian Cancer G-Protein Coupled Receptor Protein1 (OGR1, GPR68), G-protein Coupled Receptor 4 (GPR4), G2 accumulation (G2A, GPR132), and T Cell Death-Associated Gene 8 (TDAG8, GPR65)." (PMID 36010617, 2022). "Regarding GPR68 expression in different tumour cell lines, a moderately strong immunosignal was obtained only with the neuroendocrine tumour cell line BON-1 and the ovarian carcinoma cell line A2780." (PMID 31652823, 2019). "GPR68 was first cloned from the HEY human ovarian cancer cell line and named OGR1, although in keeping with revisions in nomenclature, GPR68 is now more commonly used." (PMID 30696114, 2019). "Ovarian cancer G protein coupled receptor 1 (OGR1, aka GPR68) is a proton‐sensing Gq‐coupled receptor that is most highly expressed in cerebellum." (PMID 28627017, 2017). "A protein important for pH-dependent tumor biology and sensitive to 3D structural growth is the ovarian cancer G-protein-coupled-receptor-1 (OGR1, also called GPR68)." (PMID 29245949, 2017). "The family of GPCR includes the ovarian cancer G protein-coupled receptor 1 (OGR1, also known as GPR68), the G protein-coupled receptor 4 (GPR4), the T cell death-associated G protein 8 (TDAG8, also known as GPR65), and the G2 accumulation protein (G2A, also known as GPR132)." (PMID 30825056, 2019).
prostate carcinoma (17 papers, 2009 to 2025). A carcinoma that arises from epithelial cells of the prostate gland. "GPR68 deficiency in mice reduced the size of tumors induced by xenotransplantation of cells from murine melanoma (B16-F10) or prostate cancer (TRAMP-C2, RM-9) cell lines and, in both cases, an altered macrophagic response was observed." (PMID 33113952, 2020). "Subsequent data indicated that prostate cancer tumorigenesis was reduced in GPR68-deficient mice." (PMID 30696114, 2019). "Successively, bone marrow transplantation revealed that GPR68 expression in myeloid-derived blood cells, particularly CD11b+Gr1+ double-positive cells, was required for prostate cancer cell-induced immunosuppression to sustain tumor allografts." (PMID 39336742, 2024). "Previous studies demonstrated the role of GPR68 in tumor development where GPR68 deficiency significantly reduced tumor allograft development in GPR68 knockout mouse model of prostate cancer cells." (PMID 35311103, 2022). "In the case of prostate cancer, the administration of wild type macrophages normalized the tumor growth, thus suggesting that GPR68 expression in host cells contributes to tumor induced immunosuppression." (PMID 33113952, 2020). "First identified as a metastasis suppressor gene in prostate cancer, GPR68 has also been reported to promote tumorigenesis in prostate cancer and melanoma." (PMID 30696114, 2019). "Similarly, GPR68 facilitates tumor escape from immune surveillance, and knockout of GPR68 in melanoma and prostate cancer inhibits tumor proliferation Chronic inflammation is one of the primary drivers of fibrosis." (PMID 41190345, 2025). "Also, GPR68 acts as a double‐edged sword, where it was found to be a tumor-suppressor in the prostate cancer, whereas other studies revealed that GPR68 has an oncogenic profile by promoting cancer outgrowth." (PMID 35311103, 2022). "Another study investigated the function of host cell GPR68 in prostate cancer, wherein TRAMP-C2 and RM-9 cells were subcutaneously injected into WT and GPR68-KO mice." (PMID 39336742, 2024). "GPR68 did not affect primary tumor growth; consistent with the in vivo data, overexpressing GPR68 in prostate cancer cell lines (PC3, C2-4 and DU145) inhibited cell migration, but did not affect cell proliferation." (PMID 30696114, 2019). "However, adoptive transfer of WT T cells did not significantly affect tumorigenesis in GPR68 KO mice, implying that GPR68 expression in the T cells may not be critical for tumorigenic effects in prostate cancer." (PMID 30696114, 2019).
colitis (16 papers, 2019 to 2026). Inflammation of the colon. "Further supporting a role for GPR68 in colitis-associated nociception, we found that Gpr68 expression was enriched in peptidergic subpopulations of colonic sensory neurons and showed high co-expression with Trpv1, a marker of nociceptive afferents." (PMID 41197770, 2025). "GPR68, along with other members of proton-sensing G protein-coupled receptors, responds to extracellular acidification and has been implicated in chronic inflammation-related diseases such as ischemia, cancer, and colitis." (PMID 39768215, 2024). "Furthermore, in an IL-10 knockout mouse model, GPR68 deficiency provides protection against the development of colitis." (PMID 31652823, 2019). "In experimental colitis, intestinal activation of GPR68 promotes fibrogenesis, and pharmacological inhibition attenuates inflammatory and fibrotic responses." (PMID 41595528, 2026). "Genetic and pharmacological modulation confirms GPR68’s role in visceral nociception and supports its potential as a therapeutic target for pain management in colitis." (PMID 41197770, 2025). "Expression of GPR68 in colonic nociceptors and tissue from people with colitis was confirmed by in silico analysis of our RNA-seq databases." (PMID 41197770, 2025). "Genetic deletion of GPR68 has been found to lead to reduced disease severity concerning intestinal inflammation in a colitis mouse model." (PMID 39336742, 2024). "In previous reports, GPR68 was identified to promote intestinal inflammation in the IL10-/- murine model for colitis." (PMID 39336742, 2024). "Accordingly, inhibition of GPR68 attenuates inflammation and improves the outcomes in murine disease models of colitis and chronic kidney failure-induced cardiac inflammation and fibrosis." (PMID 39768215, 2024). "This notion is further supported by the findings that GPR68 is involved in the pathogenesis of intestinal inflammation, fibrosis, and colitis, indicating its potential, yet unexplored role in the propagation of lung inflammation." (PMID 39768215, 2024). "Compared to GPR68+/+/IL-10−/− mice (a mouse model of spontaneous colitis), GPR68−/−/IL-10−/− mice have a lower incidence and delayed onset and progression of rectal prolapse, implicating a role for GPR68 in promoting experimental inflammatory bowel disease." (PMID 30696114, 2019). "To investigate the functional role of GPR68 in colitis, we used a 1.5% DSS-induced colitis model." (PMID 41197770, 2025). "Localised acidification from immune cell infiltration and heightened glycolysis contributes to colitis pathology by activating acid-sensing receptors such as G protein-coupled receptor 68 (GPR68), a proton-sensing G protein-coupled receptor (GPCR) expressed on immune and stromal cells." (PMID 41197770, 2025). "Moreover, deletion of GPR68 or GPR4 ameliorates gut mucosal inflammation in mouse model of colitis, indicating these proton‐activated GPCRs may act as a proinflammatory role in the development of colitis." (PMID 35343079, 2022). "Additionally, pharmacological inhibition of GPR68 decreases the severity of both acute and chronic dextran sulphate sodium (DSS)-induced colitis." (PMID 41197770, 2025).